TNFSF14 (TNF superfamily member 14)
Diseases named in the same sentence as TNFSF14 in open-access papers (continued):
Sharing a sentence is not in itself a finding about the gene and the disease.
soft tissue sarcoma (1 paper, 2024). A malignant neoplasm arising from muscle tissue, adipose tissue, blood vessels, fibrous tissue, or other supportive tissues excluding the bones. "We further established two hub genes (DUSP9 and TNFSF14) prognosis markers and risk scores associated with soft tissue sarcoma prognosis and immune therapy response." (PMID 38720884, 2024). "The total-gene TLS score, risk score and TNFSF14 hub gene may be useful biomarkers for predicting the prognosis and immunotherapy efficacy of soft tissue sarcoma." (PMID 38720884, 2024). "The total-gene TLS score, Risk score, and TNFSF14 hub gene might be useful biomarkers for predicting the prognosis and immunotherapy efficacy of soft tissue sarcoma." (PMID 38720884, 2024).
spontaneous abortion (1 paper, 2024). Expulsion of the product of FERTILIZATION before completing the term of GESTATION and without deliberate interference. "In summary, this study suggests that dNK cells maintain senescence homeostasis of DSCs via TNFSF14/TNFRSF14, providing a potential therapeutic strategy to prevent DSC senescence-associated spontaneous abortion." (PMID 39261664, 2024).
thymoma (1 paper, 2022). A neoplasm arising from the epithelial cells of the thymus. "In CESC, ESCA, GBM, LUSC, and thymoma (THYM), RRM2 had a negative correlation with marker genes of immune activating genes, such as VSTR, TNFSF14, TNFRSF14, and STING1." (PMID 36518297, 2022).
thyroid cancer (1 paper, 2025). "In previous analyses, we identified a significant causality between TNFSF14 and thyroid cancer and excluded reverse causality, while also finding that 36 blood metabolites and 24 blood metabolite ratios are associated with thyroid cancer risk." (PMID 40072746, 2025). "By utilizing stringent Bonferroni correction, we identified a significant association between TNFSF14 and an high risks of thyroid cancer." (PMID 40072746, 2025). "Ultimately, we identified two blood metabolites that mediated the causal effect of TNFSF14 on thyroid cancer." (PMID 40072746, 2025). "Overall, while investigating the causality between 91 inflammatory cytokines and thyroid cancer, we established a significant unidirectional causality between TNFSF14 and thyroid cancer." (PMID 40072746, 2025). "To gain a deeper understanding of the causal effect of TNFSF14 on thyroid cancer, we conducted a mediation MR analysis." (PMID 40072746, 2025). "This strongly supports the unidirectional causal role of TNFSF14 on thyroid cancer and facilitates subsequent mediation MR analysis." (PMID 40072746, 2025). "The TNFSF14 can increase the risk of thyroid cancer by raising Lactosyl-N-palmitoyl-sphingosine (d18:1/16:0) levels and X-12013 levels." (PMID 40072746, 2025). "Finally, our two-step MR analysis indicated that Lactosyl-N-palmitoyl-sphingosine (d18:1/16:0) and X-12013 have a mediating effect in the causal relationship between TNFSF14 and thyroid cancer, with mediation proportions of 8.55% and 5.78%, respectively." (PMID 40072746, 2025). "Ultimately, we identified a significant association between 5-hydroxymethyl-2-furoylcarnitine and increased risks of thyroid cancer, and found that TNFSF14 can increase the risk of thyroid cancer by elevating Lactosyl-N-palmitoyl-sphingosine (d18:1/16:0) levels and X-12013 levels." (PMID 40072746, 2025). "The IVW method revealed that genetically determined higher levels of tumor necrosis factor ligand superfamily member 14 (TNFSF14) (one-SD increase) were significantly associated with 25% higher odds of thyroid cancer (IVW-OR: 1.25, 95% CI 1.10–1.42, p = 0.0004)." (PMID 40072746, 2025). "Subsequently, we incorporated GWAS data of 1400 blood metabolites and explored whether these metabolites could potentially mediate the causal effect of TNFSF14 on thyroid cancer." (PMID 40072746, 2025). "Our study demonstrates that TNFSF14 is positively associated with the risk of thyroid cancer, and this association can be mediated by the levels of Lactosyl-N-palmitoyl-sphingosine (d18:1/16:0) and X-12013 in the blood, with mediation proportions of 8.55% and 5.78%, respectively." (PMID 40072746, 2025). "The reverse MR analysis identified suggestive causal associations between thyroid cancer and 3 inflammatory cytokines and ruled out the reverse causality between TNFSF14 and thyroid cancer." (PMID 40072746, 2025). "Therefore, we decided to further investigate the mediating role and mediating effects of these blood metabolites between TNFSF14 and thyroid cancer." (PMID 40072746, 2025). "It is important to emphasize that we found no reverse causal relationships of thyroid cancer on TNFSF14, which excludes the possibility that thyroid cancer directly causes changes in TNFSF14 levels." (PMID 40072746, 2025). "Finally, TNFSF14 or these mediating blood metabolites could be targeted therapeutically by developing inhibitors specifically directed at these inflammatory cytokines or blood metabolites, thereby aiding in the treatment of thyroid cancer and improving the prognosis of patients." (PMID 40072746, 2025).
ulcerative colitis (1 paper, 2024). An inflammatory bowel disease involving the mucosal surface of the large intestine and rectum. "Previous studies have suggested an increase in the TNF-related cytokine, TNFSF14 or LIGHT secretion from a subset of fibroblasts from ulcerative colitis patients with active inflammation." (PMID 39056656, 2024).
tumor (181 papers, 2008 to 2026). "In a recent study, researchers determined that the expression of TNFSF14 negatively correlates with tumor mutation burden (TMB) in GBM and that TNFSF14 is a significant prognostic factor for poor OS." (PMID 33429364, 2021). "Additionally, CD44 and TNFSF14 were found to be positively associated with Tregs, which are known to suppress the immune response and promote tumor growth." (PMID 39977830, 2025). "And, TNFSF14 could cause significant changes in vascular normalization and generation of tertiary lymphoid structures to regulate tumor environment." (PMID 38012562, 2023). "The results suggest that TNFSF14 is associated with higher tumor malignancy." (PMID 32310827, 2020). "Although most upregulated genes in CCS are associated with pro-tumor properties, the upregulation of TNFSF14 might have an opposite effect." (PMID 30987352, 2019). "Interestingly, BTLA, CD200, IDO1, LAG3, TNFSF14, etc., were overexpressed in the low-risk group, suggesting that low-risk patients may get better treatment outcomes in tumor immunotherapy." (PMID 38169540, 2024). "Subsequently, the functional assays verified that TNFSF14 significantly enhanced CIK-mediated tumor cell killing, degranulation, and cytokine production in ccRCC cell lines, confirming its role in enhancing CIK effector function." (PMID 42159775, 2026). "Among them, TNFSF14, an immune modulator, is particularly involved in regulating T cell activation within the tumor microenvironment." (PMID 40496862, 2025). "Conversely, genes such as TNFSF14 (LIGHT) and TNFRSF14 (HVEM), which promote anti-tumor immunity, showed higher expression in the low-risk group." (PMID 41153362, 2025). "Elevated TNFSF14 expression indicates its role in influencing the tumor microenvironment and facilitating immune evasion by tumors." (PMID 40243888, 2025). "The expression levels of TFRC, LAMC1, PLK1, TYMS, and TSSK6 were significantly higher in tumor tissues while TNFSF14 exhibited higher expression levels in normal tissues." (PMID 40496862, 2025). "DUSP9 and TNFSF14 can affect the recruitment and activation of T, B, dendritic cells, and other immune cells by changing the signaling pathways in the tumor milieu, thus affecting the efficacy of immunotherapeutic agents." (PMID 38720884, 2024). "TNFSF14, also known as LIGHT, is highly effective in driving anti-tumor immune responses and inducing changes in the tumor microenvironment." (PMID 38903709, 2024). "TNFSF14 and T cell co-stimulatory molecules can activate NK cells, but cannot directly kill tumor cells." (PMID 38720884, 2024). "As expected, the staining of primary tumor tissue and lung metastases showed that TNFSF14 was positively expressed as a prognostic protective factor, and DUSP9 was negatively expressed as a prognostic risk factor." (PMID 38720884, 2024). "Targeting LIGHT/TNFSF14 to tumor vessels through fusion to a vascular-targeting peptide (LIGHT-VTP) prolonged survival and sensitized RIP1-Tag5 pancreatic tumors to immunotherapies, while inducing formation of TLS and PNAd+ TA-HEVs." (PMID 37954592, 2023). "TNFSF14 also helps establish anti-tumor memory by stimulating the function of effector and CD8+ T cells infiltration." (PMID 37024802, 2023). "In order to address this gap in knowledge, this study combined TNFSF14/LIGHT immunomodulation with a bispecific antibody armed with activated T-cells targeted to the tumor." (PMID 35177811, 2022). "LIGHT (TNFSF14) is an immunostimulatory cytokine required for the activation of CD8 T-cells that can augment the anti-tumor immune response." (PMID 35177811, 2022). "TNFSF14 in particular has shown promise as an immunomodulator that can enhance T cell and natural killer (NK)-cell proliferation, function, and anti-tumor responses." (PMID 35582419, 2022). "Tumor necrosis factor superfamily member 14 (TNFSF14)/LIGHT+ lEVs regulate T-cell responses to tumor cells and exhibit a role in immune suppression." (PMID 36704194, 2022).
tumor (continued). "TGFBR1, PDCD1LG2, CD274, and TNFSF14 are involved in tumor immune evasion and are effective targets for tumor immunotherapy." (PMID 36371223, 2022). "Another strategy makes use of the tumor vasculature normalization aspect of the tumor necrosis factor superfamily member 14 (TNFSF14/CD258/LIGHT)/lymphotoxin-β receptor (LTβR) signaling axis coupled with its intrinsic ability to turn a “cold” tumor “hot”." (PMID 34359588, 2021). "In terms of LUAD patients, most biomarkers, including IDO1, CTLA4, LAG3, CD40, TNFRSF18, TIGIT, and TNFSF14, were significantly increased in tumor tissues with high B cell abundance compared with that of low B cell group." (PMID 34422829, 2021). "We and others demonstrated that tumor-educated platelets (TEP) can express a manifold of tumor necrosis factor superfamily members including LIGHT (TNFSF14), GITRL (TNFSF18), OX40L some of which are known immune checkpoint molecules." (PMID 33816291, 2021). "TNFSF14 is a promising cancer immunotherapy target that appears to moderate survival and apoptosis in lymphocytes and tumor cells." (PMID 34867972, 2021). "We noted that high BLCA tumor expression of TNFRSF14 or CD160 trended toward improved prognosis compared with either TNFSF14, LTA, or BTLA." (PMID 34858395, 2021). "There was a significant correlation between TNFSF14 and IDH gene mutation and tumor PRS type status." (PMID 32310827, 2020). "LIGHT (TNFSF14) is an immunostimulatory cytokine that has been shown to augment the anti-tumor immune response and whose overexpression we identified as being associated with improved overall and recurrence free survival in patients with CRLM." (PMID 23514280, 2013). "Regarding immune checkpoint genes, CD276 and NRP1 are positively correlated with the genes in our model, while TNFSF14 shows a negative correlation with these genes in the tumor immune microenvironment of high-risk patients." (PMID 40299539, 2025). "Similarly, LAMC1 showed a significant increase (P < 0.05), while TNFSF14 was significantly downregulated in tumor tissues (P < 0.0001)." (PMID 40496862, 2025). "Interestingly, there were exceptions in nine tumor types, where TNFSF14 expression was elevated in tumor tissues compared to normal brain tissue, including GBM." (PMID 39977830, 2025). "TNFSF14 showed similar staining intensities in tumor and normal tissues." (PMID 40496862, 2025). "Besides, tumor expression of TNFSF14 has a significant impact on host anti-tumor immune responses and contributes to tumor microenvironment remodeling." (PMID 37024802, 2023). "The induction of TA-HEVs which are associated with improved tumour control following combined immune activation (via ICB) and administration of LTβR agonist is closely mirrored in instances of TNF superfamily member 14 (LIGHT) delivery to the tumour microenvironment." (PMID 37287625, 2023). "TNFSF14 binds with TNFRSF14 to deliver costimulatory signals to T cells that are capable of causing significant changes in the TME and induce an anti-tumor immune response, indicating that they might be useful in enhancing cancer immunotherapy." (PMID 36002754, 2023). "When CD8+ TIL could be increased in these tumors using LIGHT (TNFSF14), durable anti-tumor regression with immune-recall responses resulted." (PMID 35177811, 2022). "Given their expression of PVR, TNFRSF14 and CD80/CD86, they might be under direct control by TIGIT+CTLA4+CSF2+TNFSF14+ tumor cells." (PMID 33968070, 2021). "TNFSF14 which is a homolog of lymphotoxin was reported to inhibit tumor growth." (PMID 19087328, 2008). "Notably, TNFSF14 expression was significantly downregulated in tumor tissues compared to adjacent normal tissues, suggesting that CRC may suppress this pathway to evade immune surveillance." (PMID 40496862, 2025). "These indicated that TNFSF14 might assist T cells and exert anti-tumor immune regulatory effects." (PMID 38720884, 2024).
tumor (continued). "Furthermore, the interaction of DUSP9 and TNFSF14 with STS immune microenvironment may be key to tumor escape." (PMID 38720884, 2024). "It has been shown that targeting TNFSF14 signaling might enhance tumor lymphocyte infiltration." (PMID 37024802, 2023). "In addition, previous studies have shown that both CD40 and TNFSF14 are important tumor suppressor factors and CD40/CD40L interaction plays a critical role in the maturation of DCs in vivo, which greatly affect APC function, namely IL-12 production, in antitumor responses." (PMID 38021165, 2023). "We then discussed the effects of other cell types on epithelial cells in tumor tissue, and the results indicated that immune cells could regulate epithelial cells through specific ligand–receptor pairs, such as TNFSF14-TNFRSF14, MIF-(CD74+CD44), IFNG-(FINGR1+IFNGR2), CXCL12-ACKR3, and CXCL11-ACKR3." (PMID 36569924, 2022). "However, only when the TNFSF14 molecule is delivered to or expressed within tumors can it exert the synergistic effect with immune checkpoint inhibitors, thereby activating the ability of immune cells to kill tumor cells." (PMID 36588677, 2022). "Therefore, it appears that TNFSF14 (LIGHT) in the tumor microenvironment may reflect or contribute to an anti-tumor immune response." (PMID 35582419, 2022). "At present, TNFSF14-based therapy has shown great efficacy in cancer immunotherapy, which can modify tumor microenvironment by normalizing tumor vessels and significantly improve the infiltration of effector infiltrating lymphocytes, thus reducing tumor burden and forming lasting anti-tumor memory." (PMID 34917609, 2021). "Our analysis reveals a dual role of T cell-macrophage crosstalk: CD4+ and CD8+ exhausted T cells drive anti-tumor M1-like TAMs activation via TNF-TNFRSF1A, TNFSF14-LTBR, and ICAM1-ITGAL/ITGB2." (PMID 42001468, 2026). "TNFSF14, also known as LIGHT, is a member of the tumor necrosis factor (TNF) superfamily that plays a pivotal role in modulating anti-tumor immune responses." (PMID 40496862, 2025). "Alternatively, TNFSF14 (Tumor Necrosis Factor Superfamily Member 14), also known as LIGHT, enhances anti-tumor immune responses by promoting vascular normalization and the generation of tertiary lymphoid structures." (PMID 40299539, 2025). "Moreover, mRNA-based approaches delivering TNFSF14 directly into dendritic cells or effector T cells may further amplify its immunostimulatory effect and help reshape an immune “cold” tumor into a “hot” one, rendering CRC more responsive to immune checkpoint blockade." (PMID 40496862, 2025). "The immunohistochemical results showed that TNFSF14 was positively expressed in the cytoplasm, DUSP9 was positively expressed in the nucleus of tumor cells, and brown-yellow staining was considered positive." (PMID 38720884, 2024). "TNFSF14 is a member of the TNF ligand family, which activates lymphoid cells and triggers the apoptosis of various tumor cells." (PMID 38229100, 2024). "Three of these proteins—IL 12, TNFSF14, and CD244—have previously been considered as useful for clinical application in cancer therapy as promoters of tumor cell apoptosis, or as therapeutic targets." (PMID 35682983, 2022). "These included genes consistent with pro-inflammatory immune responses (CD27, CD28, CD3e, CD8a, ICOS, ICOSLG, Pax5, TBX, GATA3, HLA-A, TNFSF14, GPR146), but also immune suppressive influences in the tumor immune microenvironment (CTLA-4, FoxP3, PD-1)." (PMID 36698398, 2022). "Meanwhile, we show the IHC staining of NRP1, HAVCR2, HHLA2CD44, TNFRSF18, TNFSF14, TNFRSF8, and CD276 in tumor tissues and normal tissues." (PMID 35685438, 2022). "Further, peptide–cytokine fusion compounds which specifically bind to the abnormal tumor vasculature and deliver cytokines such as TNFα and the TNF family member LIGHT (or TNFSF14) normalize tumor vessels via endothelial cells or pericytes, respectively." (PMID 33671981, 2021).